BRCA1 (BRCA1 DNA repair associated)
Diseases named in the same sentence as BRCA1 in open-access papers (continued):
Sharing a sentence is not in itself a finding about the gene and the disease.
breast cancer (continued). "By lowering BRCA1’s ability to repair DNA, the high expression of RING domain-deficient BRCA1 proteins in breast cancer cell lines increases resistance to cisplatin and PARPi, while deletion mutations in BRCA2 would result in resistance to PARPi." (PMID 37476378, 2023). "This indicates that ZNF251 haploinsufficiency confers resistance to platinum-based drugs in BRCA1-mutated breast cancer cells." (PMID 37066268, 2023). "Deleterious BRCA1 mutations are transmitted in an autosomal dominant pattern with cumulative cancer risk estimates for a 70-yr-old woman being between 40% and 87% for breast cancer and 16% to 68% for ovarian cancer." (PMID 37335020, 2023). "Among the BRCA1 germline variant carrier subgroup with at least two children, gaining over 10 pounds between ages 18 and 30 increased the risk of breast cancer diagnosed between ages 30 and 40 (OR 1.44; 95% CI 1.01–2.04)." (PMID 37628558, 2023). "Three variants in non-BRCA1/2 genes were detected in three patients (1.85% each) with a strong family history of breast cancer." (PMID 37656691, 2023). "Very‐young age at first full‐term pregnancy (<21 years) was found to decrease the risk of breast cancer by 9% for women with a BRCA1 mutation and by 17% for women with a BRCA2 mutation." (PMID 36164270, 2023). "Homologous recombination deficiency, such as that mediated by BRCA1 and BRCA2 (BRCA1/2) mutations, is associated with a high risk of breast cancer and ovarian cancer." (PMID 36717782, 2023). "The preselection based on age and family history for testing in genetics is likely to mean that the rate of BRCA1 pathogenic variants in metaplastic breast cancer is about 10-fold less based on the detection rates in all breast cancers tested." (PMID 37592173, 2023). "BRCA1-associated breast cancer is frequently a TNBC, but approximately 25% of TNBC patients carry a BRCA1 mutation, suggesting the limited application of PARPis." (PMID 37953246, 2023). "The study included patients with high-risk HER2-negative early breast cancer and germline BRCA1 or BRCA2 pathogenic variants." (PMID 37305385, 2023). "For women with breast cancer and a BRCA1 or BRCA2 pathogenic variant, bilateral mastectomy and oophorectomy have shown to improve survival." (PMID 36544278, 2023). "Breast Cancer 1 (BRCA1) and Breast Cancer 2 oncogenes are inherited as mutations associated with breast cancer." (PMID 37511995, 2023). "The biggest risk factors are age, mutations in breast cancer genes 1 or 2 (BRCA1 or BRCA2), and dense breast tissue." (PMID 36900322, 2023). "In the prospective analysis, higher BMI and adult weight gain were associated with higher postmenopausal breast cancer risk for BRCA1 carriers (HR 1.20 per 5 kg/m2, 95% CI 1.02–1.42; and HR 1.10 per 5 kg weight gain, 95% CI 1.01–1.19, respectively)." (PMID 37340476, 2023). "Impaired DNA repair pathways are considered to be the cause of several types of cancers, including XP gene loss in skin cancer, BRCA1/2 defect in ovarian and breast cancers, and mismatch repair (MMR) deficiency in colorectal cancer (Lynch syndrome)." (PMID 37408208, 2023). "In another patient with germline BRCA1-altered breast cancer and multiple reversion mutations, decreases in variant allele frequencies (VAFs) of the individual BRCA1 reversions were observed." (PMID 37277454, 2023). "Generally, diagnosis of BC at 40 years or younger tends to imply genetic susceptibility, with an increased probability of carrying a pathogenic variant in a breast cancer gene like BRCA1/2." (PMID 36821042, 2023). "Instead, oophorectomy has recently been suggested to reduce breast cancer recurrence and mortality of both BRCA1 and BRCA2 variant carriers." (PMID 37173335, 2023).
breast cancer (continued). "These variants are closely related to high lifetime risk of developing HBOC; the reported cumulative lifetime risk of breast cancer is approximately 72% and 69%, up to the age of 80 years, for BRCA1 and BRCA2 respectively." (PMID 37055759, 2023). "SNORA68 is a small nucleolar RNA (snoRNA) located at p13.1 on chromosome 19 (19p13.1) that is associated with susceptibility to ovarian and breast cancer in individuals with BRCA1 or BRCA2 mutation." (PMID 38053181, 2023). "Germline mutations of BRCA1/2 are the most concerned variants responsible for driving the susceptibility of familial breast cancer and ovarian cancer, collectively known as hereditary breast and ovarian cancers (HBOCs)." (PMID 38068930, 2023). "Pathogenic variants in high‐risk breast cancer predisposition genes (BRCA1, BRCA2, and PALB2) were found in 4.5% of older women with triple‐negative breast cancer." (PMID 36544278, 2023). "Approximately 5–10% of breast cancer cases are associated with germline BRCA1/2 pathogenic variants." (PMID 37305385, 2023). "Another systematic review evaluated the evidence of dietary habits, weight status/change, and physical activity on ovarian and breast cancer risk among women with BRCA1/BRCA2 P/LP germline variants." (PMID 37628558, 2023). "Pregnancy is associated with a reduced risk of breast cancer in BRCA1/2 carriers, the greater number of pregnancies the larger the reduction in risk was observed." (PMID 36164270, 2023). "In this particular family, the initial individual of interest, marked as III:2 within the family tree, underwent genetic testing due to the family’s notable history of breast cancer and was found to carry a pathogenic variant within the BRCA1 gene." (PMID 37958392, 2023). "Genetics also plays a pivotal role, with certain gene mutations, like Breast Cancer gene 1 & 2 (BRCA1 and BRCA2), elevating risk." (PMID 38054148, 2023). "It was further observed that beta hCG promotes migration and invasion in breast cancer cells, particularly those with BRCA1 mutation." (PMID 37580469, 2023). "A more recent study found methylation differences at only one of the CpG sites in the BRCA1 promoter in the blood of breast cancer women and pre-diagnostic breast cancer cases and again here detected methylation level difference were less than 2%11." (PMID 37752189, 2023). "Mutations in the BRCA1/2 gene lead to dysfunction of the normal cell cycle and a high risk of breast cancer." (PMID 36810560, 2023). "In this review, we first summarize and update the clinical trial results of the four FDA approved PARPi in treating cancers with BRCA1 and BRCA2 (BRCA1/2) mutations, including cancers of the breast, ovary, pancreas, and prostate." (PMID 37035242, 2023). "Future research on direct comparisons between different treatment regimens specifically targeting patients with breast cancer carrying BRCA1/2 pathogenic variants with a pre-specified adequate sample size is warranted." (PMID 36865806, 2023). "BRCA1/2 are two of the most well-known genes associated with the disease, and mutations in these genes increase the risk of developing both ovarian and breast cancer." (PMID 37239452, 2023). "In the OlympiAD study, the PARP inhibitor, olaparib, was compared with investigator’s choice chemotherapy (capecitabine, eribulin, or vinorelbine) in patients with metastatic HER2-negative breast cancer and germline BRCA1/2 pathogenic variants." (PMID 37305385, 2023). "Another problem with this acceptance is that mutations in the BRCA1 gene account for only a small fraction of the causes of breast cancer." (PMID 37206644, 2023). "Hereditary breast cancer, particularly the susceptible germline mutation BRCA1/2, is the major risk factor associated with breast cancer and corresponds to 5–10% of all breast cancers." (PMID 37510134, 2023). "Chemoprevention using tamoxifen was demonstrated to reduce contralateral breast cancer risk by 62% in BRCA1/2 mutation carriers." (PMID 36835955, 2023).
breast cancer (continued). "Of eight patients with BRCA1 germline variants who developed breast cancer, five had tamoxifen, and three received a placebo (RR 1.67; 95% CI, 0.32–10.7)." (PMID 37628558, 2023). "An additional subpopulation of CD44+/CD24+ cells of the BRCA1-mutated basal-A/basal-like breast cancer was sorted using an antibody against CD338 (ABCG2 antigen) and found to be enriched in several stemness markers." (PMID 36834918, 2023). "In contemporary management, the most pertinent example illustrating the impact of genomic profiling on breast cancer surgery is the screening for pathogenic variants of the breast cancer gene 1 (BRCA1) and/or 2 (BRCA2)." (PMID 36753055, 2023). "In breast cancer, autophagy-deficient cells exhibited a higher capacity to form metastases by degrading Neighbor to BRCA1, the autophagy cargo receptor." (PMID 36935496, 2023). "Women who have a genetic mutation of BRCA1 or BRCA2 are at a significantly higher risk for developing breast cancer." (PMID 37370730, 2023). "BRCA1 has been commonly detected mutated in breast cancers, but studies have shown BRCA1 mutations have also been associated with ovarian cancers." (PMID 37110218, 2023). "Altogether, our findings encourage including the information on germ-line pathogenic BRCA1/2 variants into the decision making for adjuvant therapy regimens of breast cancer patients." (PMID 37173335, 2023). "As previously reported for pan-cancer analysis of APOBEC-induced mutations, SBS13 mutations in BRCA1/2-proficient breast cancers associated strongly with deamination of cytidines in the lagging strand template." (PMID 37532520, 2023). "Based on one meta-analysis, the estimated mean cumulative risk for developing breast cancer by age 70 for carriers of the BRCA1 variant is 57%, whereas the risk for carriers of the BRCA2 variant is a little lower at 49%." (PMID 37781190, 2023). "The occurrence and development of tumors are associated to abnormalities in the DDR pathway, such as the mutations in the homologous recombination repair (HRR) gene BRCA1/2 in breast cancer." (PMID 37350936, 2023). "In our study, most of the patients were BRCA1 and categorized as small-range BRCA1/2 founder mutations in unselected breast cancer patients." (PMID 36620844, 2023). "About 5% of cases of breast cancer occur because of germline mutations in BRCA1 and BRCA2 and 95% remaining depend on the genetic changes in the breast cancer susceptibility gene." (PMID 37235839, 2023). "The existence of tumor-infiltrating lymphocytes in different breast cancer subtypes has been confirmed, with high frequency of infiltration of immune cells in breast cancers associated with BRCA1 and BRCA2 mutations." (PMID 37813891, 2023). "The only available data are from a single trial, which was a well-designed randomized controlled trial in a specific patient population with high-risk breast cancer carrying germline BRCA1/2 pathogenic variants." (PMID 37804479, 2023). "While potential genetic or hereditary causes like BRCA1 or BRCA2 mutations account for 5-10% of breast cancers, eight out of nine cases lack affected female reproductive systems." (PMID 37746260, 2023). "In the present study, the GIS distributions of BRCA1/2-deficient tumors were evaluated for two different major breast cancer subtypes." (PMID 37589839, 2023). "In particular, cumulating lines of evidence pointed to PARPi activity in advanced ovarian, prostate, pancreatic, and breast cancers harboring BRCA1/2 mutation." (PMID 36831640, 2023). "This is the first prospective study to analyze the association of breast cancer risk with anthropometric measures by menopausal status, separately for BRCA1 and BRCA2 variant carriers." (PMID 37340476, 2023).
breast cancer (continued). "Especially, considering that our families are selected based on a combination of multiple breast cancer cases, early onset of breast cancer, and ovarian cancer in the families, criteria that makes them very similar to the families with BRCA1/BRCA2 mutations." (PMID 37316882, 2023). "Abundant data show that patients with breast cancer with BRCA1/2 mutations (BRCA carriers) experience higher mortality rates than non‐carriers." (PMID 35778884, 2023). "In a previous study in Saudi Arabian breast cancer patients, 37 potential variants in 25 breast cancer risk associated genes other than BRCA1/2 were identified including variants in MLH1, MLH3 genes." (PMID 37656691, 2023). "The aim of this study is to characterize women with P/LP variants in BRCA1/2 genes who are followed in a High-Risk Breast Clinic, and to identify the factors that influence their choice for one of these breast cancer preventive options: RRM or IBS." (PMID 36971799, 2023). "This was not predictable considering some studies that showed a 15-year actuarial risk of contralateral breast cancer of 36.1% for women with P/LP variants BRCA1 and 28.5% for women with P/LP variants in BRCA2." (PMID 36971799, 2023). "The available data on number of cases and age of onset suggest more modest breast cancer penetrance than is typically seen in genetic clinic families with BRCA1, which fits with a missense variant with some residual function." (PMID 36927983, 2023). "For HER2-negative early breast cancer with BRCA1/2 germline mutations, a recent phase III OlympiA trial reported significant longer DFS (87.5% vs. 80.4%, p < 0.001) in the adjuvant Olaparib group compared to the placebo group." (PMID 36673082, 2023). "BRCA1 gene mutations increase susceptibility to breast cancer among carriers, but this risk is influenced by a range of factors." (PMID 37762577, 2023). "Higher young-adult BMI was associated with lower risk of premenopausal breast cancer both in BRCA1 (HR 0.75 per 5 kg/m2, 95% CI 0.66–0.84) and BRCA2 (HR 0.76 per 5 kg/m2, 95% CI 0.65–0.89) variant carriers." (PMID 37340476, 2023). "Up to 20% of breast cancer diagnoses are triple negative, with enrichment in younger patients, those of African-American descent, and known carriers of germline BRCA1 mutations." (PMID 37568617, 2023). "Individuals carrying hereditary mutations in BRCA1 have an elevated risk of developing breast cancer, and many breast tumors exhibit somatic mutations or a reduced expression of BRCA1." (PMID 37627161, 2023). "Particularly vulnerable are women with a germline (g)BRCA1/2 mutation have a risk of 69–72% of developing breast cancer and a risk of 17–44% of developing ovarian cancer by the age of 80 years." (PMID 36986126, 2023). "(LCS=742) estimated the age-specific breast cancer risk in the BRCA1/2 carriers from a prospective cohort." (PMID 37476378, 2023). "The discrimination was low (0.568), and breast cancer-associated survival good, with lower than expected mortality, similarly to the BRCA1 carriers with ER-negative breast cancer." (PMID 37173335, 2023). "To study the cellular biology of HRD tumors, we analyzed single-cell sequencing data from four normal breast tissues and four breast cancer tissues with BRCA1 pathogenic mutations that were collected during surgery." (PMID 37264024, 2023).
breast cancer (continued). "Here, we report the safety and efficacy of pamiparib in a phase II, multicenter study in Chinese patients with locally advanced or metastatic HER2− breast cancer harboring germline BRCA1/2 mutations (gBRCA1/2 m)." (PMID 36459284, 2023). "It is intriguing that breast cancers (BC) in BRCA1 mutation carriers predominantly originate from cells of the luminal lineage." (PMID 38275383, 2023). "In BRCA1-associated breast cancer, TRβ is a positive prognostic factor of OS at 5 years post-treatment, while TRα positivity predicts a reduced OS at 5 years posy-treatment." (PMID 37509273, 2023). "This network meta-analysis included patients with metastatic locally advanced or recurrent breast cancer who received pharmacotherapy and carried deleterious variants of BRCA1/2." (PMID 36865806, 2023). "Women < 40 years old have a greater relative risk of breast cancer attributable to a BRCA1 mutation, whereas 65 years is commonly used as an upper age cutoff due to previous NCCN guidelines for genetic testing in breast cancer." (PMID 37084156, 2023). "Recently, poly(ADP-ribose) polymerase (PARP) inhibitors (PARPis) have been approved by the US Food and Drug Administration for homologous recombination (HR)-deficient breast cancer induced by BRCA1/2 mutations." (PMID 37156759, 2023). "Mutations in BRCA1/2 are most common, causing a significantly increased risk of breast cancer of about 50–70% (BRCA1) and 40–60% (BRCA2) as well as of ovarian cancer of about 40–50% (BRCA1) and 15–25% (BRCA2) by 70–80 years of age." (PMID 37623237, 2023). "Cisplatin (LANS), one of the frequently prescribed drugs in breast cancer patients, especially if they have germinal mutations of the BRCA1 gene, was used as the chemotherapeutic agent." (PMID 37345102, 2023). "PARP inhibitors are used to treat homologous recombination (HR) DNA repair-deficient tumors (e.g., BRCA1/2-mutated), which was once used to treat breast cancer." (PMID 37324006, 2023). "A limited fraction of high-risk familial non-BRCA1/BRCA2 breast cancer patients is expected to benefit from treatment strategies against homologue repair deficient cancer cells." (PMID 37316882, 2023). "Rare missense variants in BRCA1 were associated with an increased risk of overall breast cancer with an adjusted OR of 2.4 (1.14-5.08 95% CI, p-value = 0.022)." (PMID 37790698, 2023). "BRCA1 accounted for the majority of variants in F1CDx and was similarly observed in ovarian and breast cancers." (PMID 37916805, 2023). "Germline (g)BRCA1/2 mutation carriers have an increased risk of developing breast cancer and are often exposed to severe cancer treatments, thus the improvement of HRQoL is important." (PMID 36986126, 2023). "A recent study also reported higher VDR expression, associated with prolonged overall survival, in BRCA1-mutated breast cancers compared to sporadic breast cancers." (PMID 37345127, 2023). "Based on these findings, the study proposed the potential use of a vaccine containing beta hCG antibodies as a treatment approach for patients with BRCA1-mutated breast cancers." (PMID 37580469, 2023). "Several other studies had attempted to answer the question of the oncological safety of BCS by comparing the outcomes of patients with BRCA1/2 mutation to a control group of patients with sporadic breast cancer." (PMID 37781190, 2023). "PARPis have proven clinical efficacy for breast cancer management and are approved for use in early and metastatic disease settings for patients with germline mutations in the BRCA1/2 genes." (PMID 37195374, 2023). "Germline BRCA1/2 variants cause hereditary breast and ovarian cancer syndrome and confer a lifetime risk of 38-87% of developing breast cancer in women and 16.5-63% of developing ovarian cancer." (PMID 37664050, 2023). "BRCA1 mutations are frequently the main driver of germ-line mutations (gBRCA), increasing breast cancer risk by 50% to 85%, especially in the triple-negative form." (PMID 37296801, 2023).